SMAD3 (SMAD family member 3)
Description:
Receptor-regulated SMAD (R-SMAD) that is an intracellular signal transducer and transcriptional modulator activated by TGF-beta (transforming growth factor) and activin type 1 receptor kinases. Binds the TRE element in the promoter region of many genes that are regulated by TGF-beta and, on formation of the SMAD3/SMAD4 complex, activates transcription. Also can form a SMAD3/SMAD4/JUN/FOS complex at the AP-1/SMAD site to regulate TGF-beta-mediated transcription. Has an inhibitory effect on wound healing probably by modulating both growth and migration of primary keratinocytes and by altering the TGF-mediated chemotaxis of monocytes. This effect on wound healing appears to be hormone-sensitive. Regulator of chondrogenesis and osteogenesis and inhibits early healing of bone fractures. Positively regulates PDPK1 kinase activity by stimulating its dissociation from the 14-3-3 protein YWHAQ which acts as a negative regulator.
Synonyms: hSMAD3; Mad3; hMAD-3; MADH3; JV15-2; HsT17436; HSPC193; LDS1C; LDS3
Tractability: Small molecule: a high-quality ligand is known; it has a binding pocket of medium quality; it belongs to a druggable protein family. Antibody: its Gene Ontology location is reachable by antibodies, with medium confidence. PROTAC: it is named in the literature on targeted protein degradation; UniProt records ubiquitination sites on it; ubiquitination databases record sites on it; its protein half-life has been measured; a small molecule that binds it is known.
Target class: Transcription factor
Gene: Protein-coding gene on chromosome 15 (67,063,763 to 67,195,173, forward strand). Ensembl gene ENSG00000166949.
Subcellular location: Cytoplasm; Nucleus
Subcellular location (Human Protein Atlas): Nucleoplasm; Basal body; Primary cilium transition zone; Vesicles
Pathways (Reactome):
Signal Transduction: Downregulation of SMAD2/3:SMAD4 transcriptional activity; Downregulation of TGF-beta receptor signaling; NOTCH4 Intracellular Domain Regulates Transcription; SMAD2/SMAD3:SMAD4 heterotrimer regulates transcription; Signaling by Activin; TGF-beta receptor signaling activates SMADs; TGFBR3 expression
Disease: SARS-CoV-1 targets host intracellular signalling and regulatory pathways; SMAD2/3 MH2 Domain Mutants in Cancer; SMAD2/3 Phosphorylation Motif Mutants in Cancer; SMAD4 MH2 Domain Mutants in Cancer; TGFBR1 KD Mutants in Cancer
Developmental Biology: Formation of axial mesoderm; Formation of definitive endoderm; Germ layer formation at gastrulation; Signaling by NODAL
Gene expression (Transcription): FOXO-mediated transcription of cell cycle genes; FOXO-mediated transcription of oxidative stress, metabolic and neuronal genes; RUNX3 regulates BCL2L11 (BIM) transcription; RUNX3 regulates CDKN1A transcription
Immune System: Interleukin-37 signaling
Metabolism of proteins: Ub-specific processing proteases
Gene Ontology:
Molecular function: bHLH transcription factor binding; cis-regulatory region sequence-specific DNA binding; co-SMAD binding; DEAD/H-box RNA helicase binding; DNA binding; DNA-binding transcription activator activity, RNA polymerase II-specific; DNA-binding transcription factor activity; DNA-binding transcription factor activity, RNA polymerase II-specific; DNA-binding transcription factor binding; DNA-binding transcription repressor activity; identical protein binding; nuclear glucocorticoid receptor binding; nuclear mineralocorticoid receptor binding; nuclear receptor binding; phosphatase binding; protein binding; protein homodimerization activity; protein kinase binding; R-SMAD binding; RNA polymerase II cis-regulatory region sequence-specific DNA binding; RNA polymerase II-specific DNA-binding transcription factor binding; sequence-specific DNA binding; sterol response element binding; transcription cis-regulatory region binding; transcription coactivator binding; and 14 more
Biological process: activin receptor signaling pathway; apoptotic signaling pathway; cell-cell junction organization; cellular response to transforming growth factor beta stimulus; extrinsic apoptotic signaling pathway; immune response; negative regulation of cell growth; negative regulation of cell population proliferation; negative regulation of cytosolic calcium ion concentration; negative regulation of fat cell differentiation; negative regulation of gene expression; negative regulation of miRNA transcription; negative regulation of ossification; negative regulation of transcription by RNA polymerase II; nodal signaling pathway; positive regulation of DNA-templated transcription; positive regulation of epithelial to mesenchymal transition; positive regulation of extracellular matrix assembly; positive regulation of gene expression; positive regulation of miRNA transcription; positive regulation of nitric oxide biosynthetic process; positive regulation of SMAD protein signal transduction; positive regulation of transcription by RNA polymerase II; regulation of DNA-templated transcription; regulation of transcription by RNA polymerase II; and 54 more
Cellular component: chromatin; cytoplasm; cytosol; heteromeric SMAD protein complex; homomeric SMAD protein complex; nuclear inner membrane; nucleoplasm; nucleus; receptor complex; SMAD protein complex; transcription regulator complex; transcription repressor complex; plasma membrane; protein-DNA complex
Genetic constraint (gnomAD): Loss-of-function variants: 12 observed, 52.18 expected, observed/expected ratio (o/e) 0.23, 90% interval 0.15 to 0.37. The upper end of that interval is the gene's LOEUF score, 0.37, which puts it in group 1 of 6, group 1 being the genes least tolerant of losing a copy. Missense variants: 294 observed, 582.05 expected, observed/expected ratio (o/e) 0.51, 90% interval 0.46 to 0.56. Synonymous variants: 238 observed, 234.45 expected, observed/expected ratio (o/e) 1.02, 90% interval 0.91 to 1.13.
Gene-disease validity (ClinGen):
ClinGen rates the evidence that SMAD3 causes each of these diseases.
aneurysm-osteoarthritis syndrome (autosomal dominant): Definitive.
Cancer hallmarks: invasion and metastasis (promotes); escaping programmed cell death (promotes); escaping programmed cell death (suppresses); proliferative signalling (promotes); suppression of growth (promotes)
Homologues: Orthologues: dog SMAD3 (100% identical), mouse Smad3 (100% identical), pig SMAD3 (100% identical), rat Smad2 (100% identical), macaque SMAD3 (99% identical), guinea pig SMAD3 (99% identical), zebrafish smad3a (97% identical), chimpanzee SMAD3 (97% identical), tropical clawed frog smad3 (96% identical), zebrafish smad3b (93% identical), rabbit SMAD3 (54% identical). Paralogues in human: SMAD2 (92% identical), SMAD1 (67% identical), SMAD5 (67% identical), SMAD9 (65% identical), SMAD4 (44% identical), SMAD6 (27% identical), SMAD7 (24% identical).
Diseases named in the same sentence as SMAD3 in open-access papers:
SMAD3 is named in the same sentence as 505 diseases in open-access papers, as found by Europe PMC text mining. Sharing a sentence is not in itself a finding about the gene and the disease. The quoted sentences say what the papers report.
renal fibrosis (400 papers, 2011 to 2026). A final common manifestation of a wide variety of chronic kidney diseases characterized by glomerulosclerosis and tubulointerstitial fibrosis. "BT173 effectively reduced UUO- and HIV-induced renal fibrosis in vivo, which was associated with reduced Smad3 phosphorylation and repression of TGF-β-responsive matrix gene expression." (PMID 39990662, 2025). "Targeting the TGF-β/Smad3 signaling pathway significantly attenuates renal fibrosis, while adeno-associated virus (AAV)-mediated delivery of the SIRT1 gene activates the NAD + salvage pathway, enhancing renal cell metabolic function." (PMID 41487503, 2025). "It is highly possible that targeting Smad3 with Smad3 inhibitors such as SIS3 inhibits renal fibrosis as well as acute kidney injury via a mechanism associated with GPX4-dependent ferroptosis as seen in this study and other previous reports." (PMID 41079940, 2025). "SMAD3 is strongly associated with renal fibrosis as SMAD3 knockout prevents fibrosis in mouse models of UUO, diabetic nephropathy, hypertensive nephropathy, and chronic aristolochic acid nephropathy." (PMID 38982119, 2024). "(2022) have shown that CP administration causes renal fibrosis via modulation of TGF-β1/Smad3 pathways, and alogliptin treatment reversed the renal fibrosis toward normal." (PMID 37559381, 2023). "In term of renal fibrosis, Smad3 is pathogenic and overreactive, whereas Smad7 is protective but lost in the fibrotic kidney." (PMID 35541902, 2022). "It is also possible that activation of renal TGF-β/Smad3 signaling results in COVID-19 associated fibrosis including lung and renal fibrosis." (PMID 35541902, 2022). "The equilibrium of Smad signaling is essential for TGF-β-mediated renal fibrosis, and Smad3 is pathogenic factor, while Smad2 and Smad7 play a protective role." (PMID 35478960, 2022). "In the context of TGF-β1/Smad signaling, Smad3 is confirmed to be pathogenic because deletion of Smad3 inhibits renal fibrosis." (PMID 35478960, 2022). "Collectively, these findings suggest that let-7i-5p is a Smad3-dependent microRNA that plays a pathogenic role in renal fibrosis." (PMID 36091385, 2022). "In the context of renal fibrosis, Smad3, a key downstream of mediator, is pathogenic, but Smad7, a negative regulator of Smad3, is protective 4-6." (PMID 36147472, 2022). "Our results demonstrated that administration of I-BET151 effectively improved renal function and ameliorated renal fibrosis in association with inhibition of TGFβ/Smad3, ERK1/2 and NF-kB signaling and suppression of inflammation." (PMID 33664670, 2021). "In contrast to the observations in Pax8-HIPK2WT UUO kidneys, the kidneys of Pax8-HIPK2KD-UUO mice showed a marked reduction in renal fibrosis, which was associated with reduced Smad3 activation and expression of profibrosis markers." (PMID 32701510, 2020). "Renal miR-29b is decreased in association with activation of TGF-β/Smad3 signaling and progressive renal fibrosis in kidney diseases." (PMID 32258028, 2020). "A deficiency of Smad3 protects against myofibroblast formation and renal fibrosis in various experimental mouse kidney injury models." (PMID 32512831, 2020). "The activation or inactivation of TGF-β/Smad signaling pathway, as reflected by the expression levels of Smad2, Smad3 and Smad7, is a pathogenic mechanism in the progression of renal fibrosis." (PMID 30101622, 2018). "TGF-β causes renal fibrosis via activation of Smad2 and Smad3 leading to complex formation with Smad425." (PMID 28743964, 2017). "Overexpression of the inhibitory Smad7 results in inhibition of renal fibrosis, while loss of renal Smad7 enhances TGF-β/Smad3-mediated renal fibrosis and inflammation." (PMID 29039786, 2017). "TGF-β receptors signal via members of the Smad family, of which Smad3 has been most clearly implicated in renal fibrosis." (PMID 26684242, 2016).
renal fibrosis (continued). "In a mouse model of chronic AAN, deletion of Smad3 gene protects against progressive renal fibrosis, revealing a pathogenic role for Smad3 in the development of chronic AAN." (PMID 25883225, 2015). "It has been well documented that Smad3-deficient mice are protected from renal fibrosis by a reduction in EMT, collagen deposition, and the expression of profibrotic TGFβ target genes." (PMID 24885228, 2014). "Enhanced renal injury in Smad7 KO mice was associated with more progressive renal fibrosis with elevated TGF-β/Smad3 signalling." (PMID 23301086, 2013). "Smad3 mediates renal fibrosis via a mechanism associated with GPX4-dependent ferroptosis." (PMID 41079940, 2025). "scRNA-seq revealed that empagliflozin modulated the TGF-β signaling pathway, inhibited intercellular communication, and reduced the expression of fibrotic genes such as Col4a1 or Fn1 that are associated with miR-192-mediated TGF-beta/SMAD3-driven renal fibrosis." (PMID 41303298, 2025). "TGF-β1 and SMAD3 are particularly pathogenic in the progression of renal fibrosis." (PMID 38637422, 2024). "Similarly, another traditional Chinese medicine, Huangqi Chifeng decoction, can improve renal fibrosis caused by IgA nephropathy through TGF‐β1/Smad3 signalling by inhibiting the secretion of exosomes containing TGF‐β1 mRNA." (PMID 38898750, 2024). "Secreted TGF-β1 caused renal fibrosis in kidney cells through Smad3 activation." (PMID 37340199, 2023). "In this case, eNOS could phosphorylate VEGF and vice-versa, protecting podocyte loss, glomerular and peritubular vascular rarefaction, renal fibrosis, and inhibiting the expression of TGFβ-Smad3." (PMID 36558475, 2022). "In summary, this study first confirmed that low dose of BV could cause obvious EMT-related renal fibrosis in vivo and in vitro, which was associated with the activation of the TGFβ1/Smad3 and Notch1/NICD signaling pathway." (PMID 35873571, 2022). "Smad4 contributes to the promotion of renal fibrosis caused by Smad3." (PMID 36648873, 2022). "By contrast, conditional knockout of Smad2 from tubular epithelial cells enhances Smad3-mediated renal fibrosis, which is associated with phosphorylation and nuclear translocation of Smad3, auto-induction of TGF-β1 expression, and transcription of collagen I and III genes." (PMID 34299192, 2021). "However, Smad3-deficient mice with UUO were protected against renal fibrosis and increased renal miR-29 expression." (PMID 33364960, 2020). "Indeed, Ang II is able to directly and indirectly activate Smad3 to cause cardiovascular and renal fibrosis via a TGF‐β‐dependent and ERK1/2‐Smad crosstalk pathway." (PMID 32971570, 2020). "The TGF-β/Smad signaling pathway exerts an important effect on renal fibrosis, while targeting the TGF-β/Smad3 signaling pathway may represent an effective treatment approach for CKD treatment that is associated with renal fibrosis." (PMID 32092824, 2020). "Furthermore, mice deficient in Smad3 were found to be protected against the upregulation of miR-21 and renal fibrosis in the UUO model." (PMID 33364960, 2020). "When released from LAP (latency-associated peptide) and LTBP (latent TGF-β-binding protein), active TGF-β1 binds with its type II receptor that activates type I receptor and downstream effectors, Smad2 and Smad3, to regulate genes associated with renal fibrosis." (PMID 31754396, 2019). "In Smad3-deficient mice, renal fibrosis is abated, which indicates that inhibition of the TGF-β signaling pathway may provide a promising strategy to treat renal fibrosis." (PMID 29271928, 2017). "Thus, results from this study revealed that treatment with TSF significantly suppressed diabetic kidney injury via mechanisms associated with NF-κB-driven renal inflammation and TGF-β/Smad3-mediated renal fibrosis." (PMID 26807792, 2016).
renal fibrosis (continued). "In conclusion, the present study establishes that macrophages are key inflammatory cells that exacerbates progressive tubulointerstitial damage in chronic AAN via mechanisms associated with TGF-β/Smad3-mediated renal fibrosis and NF-κB-driven renal inflammation." (PMID 26909597, 2016). "In the context of DN, TGF-β/Smad3 signaling is highly activated, which is associated with downregulation of renal Smad7, resulting in renal fibrosis as seen in both experimental and human diabetic kidneys and in vitro under high glucose and advanced glycation end products conditions." (PMID 24646636, 2014). "Furthermore, in vivo L-Endoglin overexpression potentiates Smad1 and Smad3 pathways and this effect is associated with higher renal fibrosis development." (PMID 25313562, 2014). "However, the mechanism linking a loss of NOS3 expression to increased renal fibrosis is most likely to involve the central TGF-β1/Smad3 pro-fibrotic signalling pathway." (PMID 24391884, 2013). "After renal mass ablation, several intracellular molecules associated with renal fibrosis, including NF-kappaB p65, Smad-3, signal transducer and activator of transcription-3 and extracellular regulated kinase 1/2, are phosphorylated; suramin treatment inhibited their phosphorylation." (PMID 22558380, 2012). "In addition, several TGF-β/Smad3-associated lncRNAs are found to be associated with renal fibrosis." (PMID 32258028, 2020). "Thus, it is possible that the renal protective effect of TSF on diabetes may be associated with the inhibition of TGF-β/Smad3-mediated renal fibrosis." (PMID 26807792, 2016). "Outcomes from this study suggested that restoring the balance of downstream TGF-β/Smad signaling with AA (a Smad7 agonist) and NG (a Smad3 inhibitor) may represent a new therapeutic approach for chronic kidney disease associated with progressive renal fibrosis." (PMID 26474462, 2015). "Thus, the imbalance of TGF-β/Smad signaling may be a major cause of renal fibrosis and rebalancing this pathway by inactivating Smad3 while upregulating Smad7 may produce a better therapeutic effect on renal fibrosis." (PMID 26474462, 2015). "In conclusion, macrophage NLRP3 is profibrotic and mediates renal fibrosis via the TGF-β/Smad3-MMT mechanism." (PMID 42157945, 2026). "Cyanoglycosides significantly reduce the expression of renal fibrosis-related proteins (TGF-β/Smad2/Smad3)." (PMID 41466459, 2026). "Mechanistically, we uncovered that NLRP3 directly bound TGF-β receptors II and I to trigger the activation of TGF-β/Smad3 signaling and progressive renal fibrosis via the macrophage-myofibroblast transition (MMT) process." (PMID 42157945, 2026). "Their actions were mediated through regulation of Smad3/7 signaling and modulation of miRNA-21 and miRNA-200b expression, highlighting these pathways as promising therapeutic targets for the treatment of renal fibrosis." (PMID 42116184, 2026). "Some studies have shown that miR-199a contributes to renal fibrosis by modulating the TGF-β/Smad3 signaling pathway and suppressing antifibrotic proteins such as caveolin-1." (PMID 40724919, 2025). "Abnormal activation of the RAS can stimulate downstream signaling pathways, such as the TGF-β/Smad3 pathway, which mediates renal fibrosis via EMT." (PMID 40699786, 2025). "Here we report a new mechanism through which Smad3 mediates renal fibrosis by downregulating the glutathione peroxidase 4 (GPX4), a central inhibitor for ferroptosis." (PMID 41079940, 2025). "Genistein improves renal fibrosis by regulating the TGF‐β/Smad3 pathway and reducing OS by activating the Nrf2‐HO‐1/NQO1 pathway." (PMID 41019174, 2025). "Smad3 is a key downstream factor of TGFβ1, and STAT3 acts downstream of many membrane receptors associated with renal fibrosis, including TGF βreceptors." (PMID 41275091, 2025).